NDRG1 (N-myc downstream regulated 1)
Diseases named in the same sentence as NDRG1 in open-access papers (continued):
Sharing a sentence is not in itself a finding about the gene and the disease.
prostate carcinoma (continued). "In conclusion, our results suggest that miR-182 plays an important role in the proliferation of human prostate cancer cells by directly suppressing the tumor supressor gene NDRG1." (PMID 23874837, 2013). "While attempting to recapitulate these findings in prostate cancer cell lines, we demonstrated that a distinct truncated form of the NDRG1 protein exists." (PMID 23634903, 2013). "While the N-terminal NDRG1 antibody gave rise to the 46 kDa full-length NDRG1 protein in all cell lysates, the C-terminal NDRG1 antibody detected the 46 kDa full-length NDRG1 protein and the 41 kDa cleaved NDRG1 protein in only the prostate cancer cell lines." (PMID 23634903, 2013). "In prostate cancer tissue, NDRG1 levels are down-regulated and NDRG1 expression has a significant inverse correlation with Gleason grade." (PMID 23634903, 2013). "Western-blot analysis of prostate cancer cell lysates identified the 41 kDa band to be a truncated form of NDRG1, with MS confirming the full and truncated proteins to be NDRG1." (PMID 23634903, 2013). "Unlike the expression of other biomarkers presented here, the expression of NDRG1 has been investigated in prostate tissue but is a subject of controversy with reports that it is increased and decreased in prostate cancer." (PMID 24386364, 2013). "In contrast, the N-terminal NDRG1 antibody gave rise to only one 46 kDa band in primary cultures of normal PrEC and all prostate cancer cell lines." (PMID 23634903, 2013). "NDRG1 (N-myc downstream regulated gene-1) is a metastasis suppressor that is down-regulated in prostate cancer." (PMID 23634903, 2013). "The expression of NDRG1 has been shown to be significantly correlated with the expression of E-cadherin in prostate cancer." (PMID 23762858, 2013). "Recent study has reported that expression of metastasis suppressor gene, KAI1 gene, is involved in NDRG1 mediated metastasis suppression of prostate cancer through ATF3-NF-κB pathway." (PMID 22844455, 2012). "NDRG1 has been shown to play a key role in stabilizing adherens junctions by upregulating recycled E-cadherin in prostate cancer cells." (PMID 21655274, 2011). "It has been demonstrated that NDRG1 plays a key role in stabilizing the adherens junctions by upregulating the recycling of E-cadherin in prostate cancer cells." (PMID 21655274, 2011). "This hypothesis is further supported by previous evidence indicating that NDRGs function as regulators of protein trafficking and that NDRG1 specifically modulates E-cadherin recycling in prostate cancer cells." (PMID 40462946, 2025). "Another approach to investigate the pleiotropic effects of NDRG1 was utilized to determine interactions with key proteins in prostate cancer and hepatocellular carcinoma cells, where NDRG1 has been elucidated to act in an anti- and pro-oncogenic manner, respectively." (PMID 40378957, 2025). "In prostate cancer, NDRG1 expression is inversely correlated with grade and overall survival." (PMID 40332138, 2025). "In this process, LINC00844 promotes the expression of N-myc downstream regulatory gene 1 (NDRG1), and NDRG1 acts as an AR repressor to inhibit AR expression, and the metastasis and differentiation of prostate cancer cells are also inhibited after the AR signaling pathway is suppressed." (PMID 39655078, 2024). "Since the nuclear translocation of p50 and p65 was facilitated by ARv7 to motivate NF-κB activity, the expressions of MALT1, prostate-specific antigen (PSA), and N-myc downstream regulated 1 (NDRG1) were therefore induced in ectopic ARv7-overexpressed prostate cancer cells." (PMID 37047218, 2023). "In the study presented here, BPH-1 cells in co-culture with CAFs exhibited an increase in NDRG1 protein expression relative to both BPH-1 monoculture and NPF-co-culture, supporting a CAF-mediated role for NDRG1 signalling in early disease stages of prostate cancer." (PMID 36765657, 2023).
prostate carcinoma (continued). "In fact, YWHAZ and NDRG1 expression levels could define two groups of prostate cancer patients with high and intermediate risks of mortality." (PMID 37249826, 2023). "In agreement with previous studies, which explored how androgen dramatically increased the NDRG1 protein expression in LNCaP cells and prostate cancer, the results of the present study confirmed further that R1881 stimulation significantly induces NDRG1 in LNCaP cells." (PMID 37047218, 2023). "Prostate cancer cell lines have been other sources for identification of the function of NDRG1." (PMID 37249826, 2023). "Similarly, NDRG1 was shown to upregulate PTEN expression in pancreatic as well as prostate cancer, a likely positive feedback loop." (PMID 36497221, 2022). "A previous study identified ATP1A1A as a potential binding partner of NDRG1 in human prostate cancer cells, raising the question of whether Ndrg1a physically interacts with ATP1A1A to bring about its downregulation." (PMID 36214665, 2022). "NDRG1 has significant scientific implications in both prostate cancer and glioblastoma." (PMID 36713580, 2022). "On the other hand, suppression of NDRG1-mediated metastasis occurs upon loss of KAI1 expression in vitro and in vivo, demonstrating that KAI1 is a functional downstream target of the NDRG1 pathway on prostate cancer." (PMID 34142021, 2021). "AR-expressing prostate cancer lines displayed varying levels of NDRG1 pS330." (PMID 33398037, 2021). "SC144-induced alterations of HIF-1α and NDRG1 were also confirmed in prostate cancer cells." (PMID 32550915, 2020). "Interestingly, an early study indicated that NDRG1 downregulated Akt phosphorylation in prostate carcinoma cells." (PMID 31581708, 2019). "Prostate cancer cells deregulate this pathway by downregulating NDRG1 to invasive property." (PMID 28371345, 2017). "Whether cellular invasiveness observed after NDRG1 knockdown leads to an increase in disseminated prostate cancer cells was the next question we addressed." (PMID 28371345, 2017). "Hence, these clinical findings demonstrate that NDRG1 has profound metastasis inhibiting capabilities in prostate cancer and other tumours." (PMID 23634903, 2013). "Fixed threshold (criteria >) values for putative biomarkers for diagnosis range between 0.68 and 0.74, indicating high sensitivity for NDRG1, BTF3 and HINT1, as diagnostic markers for identifying prostate cancer in tissue cores by unbiased, quantitative immunohistochemistry." (PMID 24386364, 2013). "It has been shown that in breast and prostate cancer, NDRG1 mRNA is differentially expressed throughout the cell cycle, peaking at the G1 and G2-M phases, with lower expression in the S phase; however, the biphasic expression of NDRG1 mRNA is absent in tumor cells." (PMID 24260043, 2013). "In fact, since tumour-associated trypsinogens are present in the DU145, PC3 and LNCaP prostate cancer cell lines, it is plausible that pseudotrypsin could cleave off NDRG1." (PMID 23634903, 2013). "A significant correlation has also been observed between NDRG1 and E-cadherin cell membrane localization, which may be a marker for malignant progression and a poor prognosis of prostate cancer." (PMID 24260043, 2013). "In addition, NDRG1 was observed to stabilize the E-cadherin protein through cellular-recycling pathways in prostate carcinoma cells." (PMID 23762858, 2013). "This post-translational modification event may decrease functional NDRG1 in prostate cancer cells that may affect its metastasis suppressor role." (PMID 23634903, 2013). "Similarly, as observed for NDRG1 overexpression inhibiting the expression of the E-cadherin transcriptional repressor, Slug, subsequent studies using prostate cancer cells indicated NDRG2 overexpression decreased expression of another E-cadherin repressor, Snail." (PMID 40378957, 2025).
prostate carcinoma (continued). "However, similar to our previous investigation examining colon and prostate cancer cells, NDRG1 overexpression in PANC-1 cells significantly increased (p < 0.001) the expression of the GSK-3β-binding protein, frequently rearranged in advanced T-cell lymphoma (FRAT1), relative to VC cells." (PMID 38815861, 2024). "Downregulation of NDRG1 in C4-2 and PC-3 prostate cancer cell lines promotes an increase in cell invasion and migration in cell culture, and suppression of AR/NDRG1 signalling has been suggested as a potential mechanism that promotes castrate-resistant prostate cancer (CRPC) progression." (PMID 36765657, 2023). "NDRG1 was also found to be expressed in the mitochondrial inner membrane in the proximal tubule cells of the kidney and was later found to weakly bind to cardiolipin, a mitochondrial inner membrane protein, in prostate cancer cells, indicating a possible role in mitochondrial apoptotic processes." (PMID 36497221, 2022). "Interestingly, NDRG1 overexpression led to an altered shape of prostate cancer cells DU145." (PMID 33104727, 2020). "A gene fusion between NDRG1 and ERG has been identified in prostate cancer, resulting in a chimeric protein in ERG overexpressed prostate cancer cells." (PMID 40862714, 2025). "This TF is well known for its role in oncogenic gene fusion products in multiple cancers including prostate cancer (TMPSSR2-ERG and NDRG1-ERG), in Ewing’s sarcoma (EWS-ERG) and acute myeloid leukemia (FUS-ERG)." (PMID 40453647, 2025). "PC cells display aberrant WNT signaling, with previous studies demonstrating that NDRG1 overexpression antagonizes the WNT/β-catenin pathway in colon and prostate cancer cells." (PMID 38815861, 2024). "For instance, in prostate cancer, GPNMB significantly inhibits cell proliferation and invasion by enhancing the expression of Ndrg1 and maspin genes." (PMID 39263169, 2024). "In this regard, NDRG1 inhibited TGFβ (transforming growth factor β)-induced Wnt/β-catenin signaling and epithelial-mesenchymal transition (EMT) in colon and prostate cancer cells." (PMID 36594086, 2023). "NDRG1 was shown to inhibit EMT in colon and prostate cancer cells by modulating the transforming growth factor beta (TGF-β) pathway, a prime regulator of EMT." (PMID 36497221, 2022). "NDRG1 overexpression has also been shown to inhibit the downstream targets of EGFR signaling, e.g., MEK1/2 or ERK1/2, in pancreatic and prostate carcinoma cells." (PMID 36160437, 2022). "In PC3 prostate cancer cells, valproic acid (VPA), a clinically available histone deacetylase inhibitor, upregulates NDRG1 expression to inhibit cancer cell invasion." (PMID 34077484, 2021). "In fact, NDRG1 up-regulation decreases the levels of pAKT (Ser473) and its downstream target mTOR, while increasing PTEN expression in prostate cancer and PC." (PMID 34572031, 2021). "Further, E6AP can suppress the metastasis suppressor n-Myc downstream regulated 1 (NDRG1) in mesenchymal phenotypes of prostate cancer where stabilization of NDRG1, via pharmacological inhibition of E6AP, has been proposed for prostate cancer therapy." (PMID 33805973, 2021). "Pharmacological agents suppressed E6AP-induced cell migration by increasing NDRG1 expression, indicating the E6AP–NDRG1 axis as an appealing target for prostate cancer therapy." (PMID 32882786, 2020). "In prostate carcinoma cells, MIEN1 provoked Akt phosphorylation; moreover, MIEN1 downregulated N-myc downstream regulated 1 (NDRG1) but upregulated interleukin-6 (IL-6) gene expression." (PMID 31581708, 2019).
prostate carcinoma (continued). "Initially, to elucidate the molecular role of NDRG1 on regulating the activation of c-Src, we utilized two established models, namely DU145 prostate cancer cells and HT29 colon cancer cells that stably over-express exogenous human NDRG1 (denoted as “NDRG1”)." (PMID 25860930, 2015). "Incubation of prostate epithelial cells and the DU145 prostate cancer cell line with DFO or Dp44mT increased expression of tumor-suppressive PTEN and anti-metastatic NDRG1." (PMID 26125440, 2015). "In summary, our data indicate that NDRG1 protein is being proteolytically cleaved at its N-terminus in the tumour metastasis-derived DU145, PC3 and LNCaP human prostate cancer cell lines." (PMID 23634903, 2013). "We then employed a quantitative immunofluorescence approach to stratify prostate cancer using co-localization coefficients of BTF3, HINT1 and NDRG1." (PMID 24386364, 2013). "Additionally, miR-182 promotes prostate cancer cell proliferation and invasion by directly targeting the 3′-UTR of NDRG1." (PMID 40332138, 2025). "A recent investigation demonstrated that the truncated NDRG1 isoform was observed only in prostate cancer cells and not in normal prostate epithelial cells, suggesting a pro-oncogenic role of NDRG1." (PMID 38983911, 2024). "In prostate cancer cells, NDRG1 knockdown increased expression of SMAD complex and overexpression of NDRG1 resulted in the opposite thus suggesting that NDRG1 limits the SMAD induced upregulation of Snail/Slug, and rescues the repression of E-cadherin expression." (PMID 36497221, 2022). "Our present study found that the ectopic overexpression of WISP1v1 but not WISP1v2 enhanced the proliferation and invasion of prostate carcinoma PC-3 cells via the downregulation of NDRG1." (PMID 36232736, 2022). "Both DHT and enzalutamide had the anticipated impact on canonical AR genes (FKBP5 and NDRG1) in an androgen-sensitive prostate cancer cell line and in differentiated hBECs (Donor B1)." (PMID 35110354, 2022). "The phosphorylation of NDRG1 by SGK1 at Ser330, but not Thr346, was associated with nuclear localization, and the cytosolic form of the pNDRG1-pT346 was predominant in prostate cancer cells." (PMID 35563887, 2022). "The over-expression of NDRG1 results in the up-regulation of epithelial markers such as β-catenin and E-cadherin in colon and prostate cancer, while differentiation-promoting ligands such as PPAR-γ, vitamin D and isobutyl methylxanthine have been demonstrated to induce NDRG1 expression." (PMID 34572031, 2021). "In one study, NDRG1 demonstrated its capacity to suppress metastasis progress without altering tumor progression in an in vivo prostate cancer model." (PMID 34142021, 2021). "The 41kDa band represented the truncated isoform of NDRG1, which is expressed in prostate cancer cell lines; PC3, DU145, LNCaP but not normal prostate cells PrEC." (PMID 33520115, 2021). "NDRG1 upregulation mediated through iron chelation has been shown to elevate PTEN expression levels in DU145 (prostate cancer cells), PrEC (normal prostate epithelial cells), but not PC3 (prostate cancer cells), which harbour a homozygous deletion in PTEN." (PMID 33520115, 2021). "Accordingly, the modulation of Akt signaling in the gene expressions of NDRG1 and IL-6 may account for the functions of MIEN1 in cell proliferation, invasion, and tumorigenesis in prostate carcinoma cells." (PMID 31581708, 2019). "Similarly in prostate cancer, NDRG1 overexpression was shown to increase PTEN expression and reduce the cellular level of phospho-Akt, while silencing of NDRG1 achieved the opposite effect." (PMID 27447861, 2016).
prostate carcinoma (continued). "We also detected an increase in NDRG1 expression in another metastatic prostate cancer cell line DU145, but not in LNCaP (data not shown)." (PMID 26692161, 2015). "Of interest, recent studies demonstrated that NDRG1 is proteolytically cleaved at the N-terminus in the prostate cancer cell lines DU145, PC3 and LNCaP, but not in normal prostate epithelial cells." (PMID 26125440, 2015). "In this report we demonstrated that NDRG1 is upregulated by VPA in highly metastatic prostate cancer cells but not in non-metastatic prostate cancer cells." (PMID 26692161, 2015). "We chose four genes BTF3, NDRG1, HINT1 and ODC1 that are up-regulated in prostate carcinoma (oncomine.org; selection criteria: p=0.0001, 2 fold change and in top 10% of genes over-expressed in the overall dataset) in at least four normal vs cancer prostate gene expression analysis datasets." (PMID 24386364, 2013). "NDRG1 gene is also an ETS-family fusion partner in ERG-expressing prostate cancer but unlike TMPRSS2-ERG and SCL45A3-ERG fusions, prevalent in prostate cancers, the NDRG1-ERG fusion is thought to encode for a chimeric protein." (PMID 24386364, 2013). "BTF3, HINT1, NDRG1 and ODC1 could be developed as epithelial specific biomarkers for tissue based diagnosis and stratification of prostate cancer." (PMID 24386364, 2013). "We used quantitative immunohistochemistry to show that the expression of BTF3, HINT1, NDRG1 and ODC1 proteins is increased in prostate cancer tissue and could serve as putative targets for the investigation of carcinogenesis or biomarkers for disease." (PMID 24386364, 2013). "In contrast to past studies using other cell-types, in the current investigation, phosphatase treatment of DU145 prostate cancer cell lysates did not lead to depletion of the 46 kDa NDRG1 protein band." (PMID 23634903, 2013). "In prostate cancer, miR‐182 upregulation activates hypoxia‐inducible factor 1α (HIF1α) signaling by targeting and inhibiting HIF‐1 (FIH1) and prolyl hydroxylase domain enzymes (PHD); it also induces cell proliferation and invasion by targeting the c‐myc downstream‐regulated gene 1 (NDRG1)." (PMID 39617640, 2024). "Second, our study highlights a distinctive difference in the effect of NDRG1 overexpression in PC cells relative to our previous findings using colon and prostate cancer cells where no significant (p > 0.05) change in total GSK-3β levels or its activation was observed." (PMID 38815861, 2024). "In HCC specifically, the suppression of NDRG1 expression and function, including disruption of its interactions with GSK-3β and Nur77, are all potential means of therapeutic interventions, although in prostate cancer, the reverse may be beneficial." (PMID 26359353, 2015). "Interestingly, over-expression of NDRG1 in breast, pancreatic and prostate cancer cell lines result in suppression of metastasis without suppression of tumorigenicity." (PMID 26431493, 2015). "From these data, we hypothesize that VPA exerts its anti-tumor activity more specifically in metastatic prostate cells than in non-metastatic prostate cancer cells, in part, by upregulating NDRG1 expression in metastatic prostate cells." (PMID 26692161, 2015). "No information exists regarding NDRG1 protein expression in prostate cancer; whether found to be fused to ERG or not, NDRG1 could be a useful protein biomarker for prostate cancer." (PMID 24386364, 2013). "Notably, this truncated version is detected specifically in prostate cancer cells and not in mortal prostate epithelial cells, which suggests this NDRG1 truncation event may have a pathological relevance and could impact NDRG1 interactions and cellular distribution." (PMID 40378957, 2025). "It has been suggested that both IL-6 and NDRG1 are modulated by Akt signal pathways; however, no report has yet studied the correlations among MIEN1, Akt, IL-6, and NDRG1 in human prostate cancer." (PMID 31581708, 2019).